BCL2L1 (BCL2 like 1)
Diseases named in the same sentence as BCL2L1 in open-access papers (continued):
Sharing a sentence is not in itself a finding about the gene and the disease.
Sepsis (22 papers, 2008 to 2025). Sepsis is defined as life-threatening organ dysfunction caused by a dysregulated host response to infection. "BCL2L1 encodes Bcl-xL, an anti-apoptotic protein that promotes cellular survival during stress responses, though its dysregulation may impair immune homeostasis in sepsis." (PMID 40362669, 2025). "In the Severe vs. Control group, the genes associated with ER stress, including CLU (p = 0.01), BCL2L1 (p = 0.015), USP14 (p = 0.046), BFAR (p = 0.004), and OPA1 (p = 0.012), demonstrated a significant positive correlation with sepsis score." (PMID 40867920, 2025). "In contrast, the transcript levels of anti-apoptotic genes, such as BCL2L11 and BCL2L1, were upregulated only in the sepsis group, wherein that of BCL2 was downregulated in both the groups." (PMID 36443881, 2022). "In addition, the present study demonstrated that both CREB3L2 and BCL2L1 were upregulated and were identified as positively correlated with one another as well as with the sepsis score." (PMID 40867920, 2025). "Moreover, transcript levels of the pro-apoptotic genes BAK1, CYCS, BBC3, CASP7, and CASP8 were upregulated in the COVID-19 cohort, whereas those of anti-apoptotic genes, such as BCL2L11 and BCL2L1, were upregulated in the sepsis cohort." (PMID 36443881, 2022). "The levels of CLU, BCL2L1, USP14, PTPN1, OPA1, and CREB3 were elevated during sepsis and demonstrated a positive correlation with sepsis score." (PMID 40867920, 2025). "A PPI network identified key hub genes, including IGLL5, BCL2L1, TNFSF10, and SNCA, with significant connections, highlighting their critical roles in sepsis development and potential as biomarkers or therapeutic targets." (PMID 40362669, 2025). "Furthermore, a positive correlation was observed between cAMP responsive element binding protein 3 like 2 (CREB3L2) and BCL2L1, as well as between the expressions of USP14 and YOD1 deubiquitinase (YOD1) in sepsis." (PMID 40867920, 2025). "This study presents findings on several genes linked to ER stress, including CLU, BCL2L1, USP14, BFAR, and OPA1, which showed a positive correlation with sepsis score and a negative correlation with the combined activities of antioxidant enzymes." (PMID 40867920, 2025). "Whether apoptosis primarily has protective or harmful consequences during systemic inflammation is still unknown but CASP3, BCL2L1, FAS, and BID are all reported to be differentially expressed in human patients suffering from different stages of sepsis." (PMID 26076814, 2015).
triple-negative breast carcinoma (20 papers, 2014 to 2025). An invasive breast carcinoma which is negative for expression of estrogen receptor (ER), progesterone receptor (PR), and human epidermal growth factor receptor 2 (HER2). "On the other hand, the hyperphosphorylation of Brd4 due to the downregulation of the phosphatase PP2A and elevated expression ratio of BCL2L1/BCL-XL has also been reported to contribute to BET inhibitor resistance in triple-negative breast cancer." (PMID 37049806, 2023).
chondrosarcoma (18 papers, 2008 to 2024). A malignant cartilaginous matrix-producing mesenchymal neoplasm arising from the bone and soft tissue. "Thus, we showed that miR-342-5p directly post-transcriptionally inhibits the anti-apoptotic BCL2 and BCL2L1 mRNAs and that miR-491-5p directly post-transcriptionally inhibits BCL2L1 mRNA in SW1353 chondrosarcoma cells." (PMID 35337159, 2022). "Moreover, as in our previous study on chondrosarcomas, we also clearly identified its binding site at position 679-686 of BCL2L1-3′UTR." (PMID 35337159, 2022). "Therefore, as previously reported in other cancer cells, BCL2L1 mRNA is also a direct target of miR-491-5p in the SW1353 chondrosarcoma cell line." (PMID 34070455, 2021). "In the present study, using functional high-throughput miRNA screening and miRNA target prediction, we selected five miRNAs that can induce apoptosis in the SW1353 chondrosarcoma cell line by targeting BCL2, BCL2L1 or MCL1 mRNAs." (PMID 34070455, 2021).
diabetes (17 papers, 2002 to 2025). "Based on previous studies, we can hypothesize that Bcl2l1 may be upregulated in response to the adverse effects of a high glucose environment on the myocardium in patients with diabetes, as a reactive mechanism to resist these effects." (PMID 38961143, 2024).
head and neck squamous cell carcinoma (16 papers, 2010 to 2025). A squamous cell carcinoma that arises from any of the following anatomic sites: lip and oral cavity, nasal cavity, paranasal sinuses, pharynx, larynx, and salivary glands. "Overexpression of antiapoptotic proteins such as BCL2, BCL2L1/BCL-XL, and MCL1, on the other hand, negatively correlates with response to cisplatin in ovarian or head and neck squamous cell carcinoma (HNSCC) patients." (PMID 34645978, 2021).
Stroke (16 papers, 2011 to 2025). Sudden impairment of blood flow to a part of the brain due to occlusion or rupture of an artery to the brain. "The anti-apoptotic protein BCL2L1 binds with BECN1 as a suppressor of autophagy, while their expression changed in the opposite direction, indicating a more complicated situation of autophagy in CE stroke." (PMID 37305740, 2023).
non-Hodgkin lymphoma (13 papers, 2016 to 2024). Distinct from Hodgkin lymphoma both morphologically and biologically, non-Hodgkin lymphoma (NHL) is characterized by the absence of Reed-Sternberg cells, can occur at any age, and usually presents as a localized or generalized lymphadenopathy associated with fever and weight loss. "In addition, mice receiving the combination treatment showed an increased expression of Bcl2l1 (encoding the navitoclax target BCL-xL), raising the possibility that, as has been observed in models of non-Hodgkin lymphoma, increased BCL-xL levels may contribute to BCL-2/BCL-xL inhibitor resistance." (PMID 38161426, 2024).
atherosclerosis (12 papers, 2013 to 2025). A disease characterized by the build-up of fatty material and calcium deposition in the arterial wall resulting in partial or complete occlusion of the arterial lumen. "Hence, in addition to the decrease in triglyceride levels and changes in lipid metabolism related genes expression, the decrease in apoptosis-related genes such as Bcl2-like 1 and Bid may also help to reduce risk of atherosclerosis and restore normal aorta vasorelaxation." (PMID 24194784, 2013). "Within this variation, a specific tsRNA (tRF-60:76-Val-AAC-1-M5) influences the therapeutic heterogeneity of sacubitril/valsartan by targeting Tnfrsf10b (tumor necrosis factor receptor superfamily 10B) and Bcl2l1 (BCL2-like 1) in lipid and atherosclerosis signaling pathways." (PMID 40247912, 2025). "In this study, our group used unmodified tRF fragments for overexpression research and confirmed that tRF-60:76-Val-AAC-1-M5 might target Tnfrsf10b and Bcl2l1 to influence the therapeutic heterogeneity of sacubitril/valsartan through the lipid and atherosclerosis signaling pathway." (PMID 36247465, 2022). "Moreover, tRF-60:76-Val-AAC-1-M5 might target Tnfrsf10b and Bcl2l1 to influence the observed therapeutic heterogeneity through the lipid and atherosclerosis signaling pathways." (PMID 36247465, 2022). "Moreover, tRF-60:76-Val-AAC-1-M5 might target Tnfrsf10b and Bcl2l1 to influence this therapeutic heterogeneity through the lipid and atherosclerosis signaling pathway." (PMID 36247465, 2022). "In rat atherosclerosis PCR array, Abca1, Bax, Bcl2, Bcl2a1, Cd44, Fabp3, Hbegf, Lypla1, Ptgs1, Selplg, Tgfb2, Tnc, and Vegfa had reverse trend between WT and MU groups, while the trends of Bcl2l1, Bid, Birc3, Cxcl1, Fas, Fn1, Itga2, Itga5, Lif, Nfkb1, Nr1h3, Ppard, and Sod1 were consistent." (PMID 34545275, 2021). "A total of 6 genes were enriched in the lipid and atherosclerosis signaling pathway (CAMK2B, VAV3, PLCB3, NFATC3, TNFRSF10B, and BCL2L1), and these genes were regulated by tRF-60:76-Val-AAC-1-M5." (PMID 36247465, 2022). "There were six targets in the intersection with 137 candidate therapeutic targets of XFZYD, which included upregulated PTGS2, MMP9, and BCL2L1 and downregulated JUN, VEGFA, and CXCL2 in the atherosclerosis group." (PMID 33425996, 2020).
endometrial cancer (12 papers, 2007 to 2025). Primary or metastatic malignant neoplasm involving the endometrium (mucous membrane that lines the endometrial cavity). "The gene BCL2L1 showed a large variation in expression among endometrial cancer patients at 5 weeks with an 11.8-fold increase for patient E2 while other patients showed no modification of expression." (PMID 28443095, 2017).
COVID-19 (11 papers, 2020 to 2024). A disease caused by infection with severe acute respiratory syndrome coronavirus 2. "BCL2L1 is known to be highly upregulated in inflamed tissue, and it was found to be upregulated in COVID-19 and both single and recurrent VTE, while CASP4 directs the noncanonical upregulation of inflammasomes." (PMID 34071557, 2021). "The high correlation strength for each cohort suggests BCL2L1 is involved in both COVID-19 and recurrent VTE but functions in opposite ways." (PMID 34071557, 2021). "The reduced expression of AKT1/2 suggests decreased cell survival, which, coupled with reduced BCL2L1 expression, may contribute to increased apoptosis and lymphopenia in COVID-19." (PMID 38389037, 2024). "The published reports also show BCL2L1 upregulates in COVID-19 patients." (PMID 38365632, 2024). "BCL2L1 was found to be upregulated in COVID-19 and both VTE cohorts." (PMID 34071557, 2021). "BCL2L1 and CASP4 were the only genes found to be dysregulated in both COVID-19 and VTE and also correlated with similar pathways in both patient cohorts." (PMID 34071557, 2021). "However, these apoptotic gene signatures were characterized by distinct DEGs expressed in the COVID-19(+) TV (BCLAF1, BCL2L1) and COVID-19(-) PU control groups (BAD, ACIN1, HIF1A)." (PMID 37026002, 2023). "Interestingly, in both COVID-19 and single VTE, BCL2L1 expression is negatively correlated to canonical pathway expression, but in recurring VTE they are positively correlated." (PMID 34071557, 2021).
head and neck cancer (11 papers, 2005 to 2022). A primary or metastatic malignant neoplasm affecting the head and neck. "In Head and Neck Cancer, SRSF10 regulates the splice variants of BCL2 Like 1 and Pyruvate kinase M to promote tumorigenesis." (PMID 35296659, 2022). "The expression of BCL2L1 in head and neck cancer patients was low reaching 1.5-fold increase at week 5 for patient N4 but the remaining patients showing no increase in expression." (PMID 28443095, 2017). "For example, genes that play a role in the inflammatory response such as ARG1, BCL2L1 (upregulated) and MYC (downregulated) were found in blood of patients undergoing radiotherapy treatment for endometrial or head and neck cancers." (PMID 34638945, 2021).
adenoma (10 papers, 2009 to 2025). A neoplasm arising from the epithelium. "In particular, gene amplification and/or overexpression of CCND1 have been associated with poor prognosis and reduced overall survival in CC patients whereas BCL2L1 has been shown to play a role in the adenoma-to-carcinoma progression." (PMID 29755661, 2018). "We analyzed the apoptosis status in LST-adenomas because BCL2L1 worked as anti-apoptosis and the apoptosis status in adenoma was less complex than cancer." (PMID 26048755, 2015). "With respect to apoptosis status in LST-Adenoma, it assumes that BCL2L1 is anti-apoptotic protein, the samples such as BCL2L1 positive and TUNEL negative, or BCL2L1 negative and TUNEL positive are consistent with the assumption." (PMID 26048755, 2015). "As a result, BCL2L1 expression was related to apoptosis status in LST-adenoma samples." (PMID 26048755, 2015). "Of the LST-adenomas, 25 (66 %) were BCL2L1 positive and 38 (100 %) were TNFRSF25 positive." (PMID 26048755, 2015). "As a result of K-means clustering, the expression levels of five genes, AKT1, BCL2L1, ERBB2, MTA2 and TNFRSF25, were found to be significantly up-regulated (p < 0.05) in LST-adenoma, compared to Ip-adenoma." (PMID 26048755, 2015). "By K-means clustering, the expression levels of five genes, AKT1, BCL2L1, ERBB2, MTA2 and TNFRSF25, were seen to be significantly up-regulated (p <0.05) in LST-adenoma compared to Ip-adenoma." (PMID 26048755, 2015). "In high grade adenoma, 14 out of 20 LST cases (70 %) showed high expression of BCL2L1 by IHC, on the contrary, only 7 out of 17 Ip adenoma cases (41 %) showed high expression of it (p = 0.078, chi-squared test)." (PMID 26048755, 2015). "Immunohistochemical analysis showed that the BCL2L1 protein was significantly and meaningfully up-regulated in LST-adenoma compared to Ip-adenoma (p = 0.010)." (PMID 26048755, 2015). "Immunohistochemical staining showed that BCL2L1 and TNFRSF25 proteins were significantly up-regulated in LST-adenoma, compared to Ip-adenoma (p = 0.010, p < 0.001)." (PMID 26048755, 2015). "In 20 low-grade LST-adenoma, ten were BCL2L1 positive and TUNEL negative, two were BCL2L1 negative and TUNEL positive." (PMID 26048755, 2015). "In 18 high-grade LST-adenoma, ten were BCL2L1 positive and TUNEL negative and two were BCL2L1 negative and TUNEL positive." (PMID 26048755, 2015).
Alzheimer disease (10 papers, 2007 to 2025). A progressive, neurodegenerative disease characterized by loss of function and death of nerve cells in several areas of the brain leading to loss of cognitive function such as memory and language. "Interestingly, AKT1, MAPK8, BCL2L1, FOXO3, and CTNNB1 were not only significantly associated with pathogenic genes (APP, MAPT, and PSEN2) but also with longevity in Alzheimer’s Disease." (PMID 36620771, 2022).
cholangiocarcinoma (10 papers, 2006 to 2024). A carcinoma that arises from the intrahepatic biliary tree (intrahepatic cholangiocarcinoma) or from the junction, or adjacent to the junction, of the right and left hepatic ducts (hilar cholangiocarcinoma). "Anti-apoptotic protein Bcl-xL encoded by BCL2L1 was identified as a prognostic marker in cholangiocarcinoma depending on anatomical subtypes when it indicated beneficial prognosis, especially for pCCA." (PMID 37197436, 2023).
follicular lymphoma (10 papers, 2013 to 2024). Follicular lymphoma is a form of non-Hodgkin lymphoma characterized by a proliferation of B cells whose nodular structure of follicular architecture is preserved. "BCL-2 was first described to be constitutively expressed in follicular lymphoma, and the amplification of MCL1 and BCL2L1 (encoding BCL-xL) are the most frequent in solid cancers." (PMID 33023187, 2020).
ischemic stroke (10 papers, 2017 to 2025). A stroke disorder caused by obstruction of blood flow to the brain, due to thrombotic (local blood clot formation) or embolic (due to a blood clot or other material traveling from another site) event. "Further, Atad1 phenocopies Bcl2 and Bcl2l1 in the middle cerebral artery occlusion mouse model of ischemic stroke: deletion of Atad1 or Bcl2 exacerbates, and overexpression of Atad1, Bcl2, or Bcl2l1 decreases ischemic cell death." (PMID 36409067, 2022). "Among these genes, NMAT1 and BCL2L1 are responsible for reducing cell death and apoptosis after ischemic stroke." (PMID 35091962, 2022).
mantle cell lymphoma (10 papers, 2015 to 2024). Mantle cell lymphoma is a rare form of malignant non-Hodgkin lymphoma affecting B lymphocytes in the lymph nodes in a region called the ``mantle zone''. "Compared to healthy controls, BCL2L1 was underexpressed in chronic leukemias, but upregulated in mantle cell lymphoma and in some acute leukemia patients." (PMID 34202143, 2021). "More recently, genes targeted through activation of ROR1 signaling (e.g., ERK1/2 or NF-κB target genes) have been defined, including the BCL2L1 gene encoding BCL-XL, which may enhance resistance to venetoclax in CLL or mantle-cell-lymphoma." (PMID 35418613, 2022).
rhabdomyosarcoma (9 papers, 2011 to 2024). A rare aggressive malignant mesenchymal neoplasm arising from skeletal muscle. "FGFR4 was previously recognized as an upstream signaling pathway that activates BCL2L1 to combat apoptosis in rhabdomyosarcoma." (PMID 34351305, 2021).
liver fibrosis (8 papers, 2014 to 2025). "Down-regulation of several miRNAs (ssc-miR-363, ssc-miR-222, and ssc-miR-106a) targeting mRNAs coding for anti-apoptotic mitochondrial genes (BCL2L11 and BCL2L1) was also observed and suggests a reduction in cellular toxic insult and death corresponding to a reduction in hepatic fibrosis." (PMID 40040391, 2025).
squamous cell carcinoma (8 papers, 2013 to 2024). A carcinoma arising from squamous epithelial cells. "This can be observed in the modulation of BCL2 family protein levels by ROS, as heightened pro-apoptotic BAX and BAK1 levels accompanied by a decrease in anti-apoptotic BCL2 and BCL2-like 1 (BCL2L1/BCL-XL) expression are observed in squamous cell carcinoma cells." (PMID 39090114, 2024).
Hodgkins lymphoma (7 papers, 2013 to 2025). A heterogeneous group of malignant lymphoid neoplasms of B-cell origin characterized histologically by the presence of Hodgkin and Reed-Sternberg (HRS) cells in the vast majority of cases. "MiR-135a promotes the apoptosis of classical Hodgkin lymphoma by mediating downregulated expression of Janus kinase 2 (JAK2) and decreasing the anti-apoptotic gene Bcl-xl (BCL2L1) expression." (PMID 32710726, 2020). "In classic Hodgkin lymphoma, miR-135a mediates Janus kinase 2 (JAK2) downregulation and decreases both the mRNA and protein levels of the anti-apoptotic gene Bcl-xL (BCL2L1), leading to apoptosis." (PMID 27486383, 2016).
gastric tumors (6 papers, 2017 to 2025). "With this approach we identified MDM2 ligase, coupled with inhibitors of the targets BCL2L1, BRD4, CDK9, PLK1 and MCL1 in stomach tumor tissue, as a therapeutic strategy." (PMID 35249548, 2022).
heart failure (6 papers, 2012 to 2023). Inability of the heart to pump blood at an adequate rate to meet tissue metabolic requirements. "NKX2-5, HSPB7 and BCL2L1 were also involved in failure of heart." (PMID 32423033, 2020). "The mRNA expression of BCL2L1 and MET was increased after ginsenoside Rg3, ginsenoside Rg5, and pseudoginsenoside F11 treatment, indicating that these three components may protect cardiomyocytes from damage by inhibiting apoptosis to improve heart failure." (PMID 36313322, 2022).
Hypertension (6 papers, 2016 to 2025). The presence of chronic increased pressure in the systemic arterial system. "In the hypothalamus of WAG rats, Npas4 gene expression correlates statistically most significantly with the expression of other DEGs, among which the Bcl2l1 gene is associated with hypertension and four DEGs encode TFs (Isl1, Hnrnpr, Mlxipl, and Zfp189)." (PMID 38928385, 2024).
myelofibrosis (4 papers, 2012 to 2026). A partial or complete replacement of the bone marrow stroma by fibrous tissue. "Overall, these preliminary findings suggest that BCL2 and BCL2L1 expression, individually and via a simple CS, predict response to ruxolitinib in myelofibrosis." (PMID 41287119, 2025). "Here, we evaluated baseline and on-treatment expression of BCL2, BCL2L1 (encoding BCL-xL), and MCL1 in 19 myelofibrosis patients receiving ruxolitinib." (PMID 41287119, 2025).
pancreatic ductal adenocarcinoma (4 papers, 2016 to 2026). An infiltrating adenocarcinoma that arises from the epithelial cells of the pancreas. "Previous literature revealed that the upregulation of TGFB2 expression can mediate epithelial-mesenchymal transition of pancreatic ductal adenocarcinoma, and MET, IRS1, and BCL2L1 are also demonstrated to be related to PAAD initiation, progression, and metastasis." (PMID 34777634, 2021).
psoriasis (4 papers, 2020 to 2025). An autoimmune condition characterized by red, well-delineated plaques with silvery scales that are usually on the extensor surfaces and scalp. "Secondly, RELA, MAPKs, JUN, and BCL2L1 are associated with the aberrant biological behaviours of keratinocytes in psoriasis." (PMID 32655662, 2020).